GABRP (gamma-aminobutyric acid type A receptor subunit pi)
Diseases named in the same sentence as GABRP in open-access papers (continued):
Sharing a sentence is not in itself a finding about the gene and the disease.
ovarian carcinoma (4 papers, 2017 to 2025). A malignant neoplasm originating from the surface ovarian epithelium. "Utilizing the SK-OV-3 ovarian carcinoma cell lines, several gain-of-function and loss-of-function studies were performed to analyze the role of GABRP in cellular migration and invasion." (PMID 34790061, 2021). "Furthermore, we performed GABRP gain- and loss-of-function studies in the SK-OV-3 ovarian carcinoma cell line to investigate the effect of GABRP on cell migration and invasion." (PMID 28524180, 2017). "Thus, in this study, we performed GABRP gain- and loss-of-function studies in the SK-OV-3 ovarian carcinoma cell line to investigate its role in ovarian cancer metastasis." (PMID 28524180, 2017). "GABRP enhances ovarian carcinoma cell metastasis through activation of mitogen-activated protein kinase/extracellular signal-regulated kinase." (PMID 35846884, 2022). "An in vivo ovarian cancer study detected a >2-fold increase in the transcriptional expression levels of GABRP in metastatic implants of human ovarian carcinoma xenografts in mice compared to SK-OV-3 ovarian carcinoma cells." (PMID 34790061, 2021). "The results showed that GABRP promoted cell migration and invasion of ovarian carcinoma cells, suggesting it has an essential role in the acquisition of an aggressive phenotype in ovarian cancer cells." (PMID 28524180, 2017). "Similar results were also observed in patients who were in the advanced stages of ovarian cancer, implying that the transcriptional regulation of GABRP is governed by a DNA methylation-dependent epigenetic mechanism which further ameliorates the aggressive phenotype of ovarian cancer." (PMID 34790061, 2021). "The involvement of GABRP in ERK regulation was further highlighted when the administration of U0126, a MAPK/MEK inhibitor, eliminated the invasive and pro-migratory abilities of SK-OV-3 cells, suggesting that GABRP modulates the MAPK/ERK pathway to enhance the metastatic potential of ovarian cancer." (PMID 34790061, 2021). "Similarly, in this study, we showed that levels of GABRP were markedly upregulated in metastatic tissues from an ovarian cancer xenograft mouse model compared with those of SK-OV-3 cells." (PMID 28524180, 2017). "Finally, treatment with the MEK inhibitor U0126 suppressed the migratory and invasive abilities of ovarian carcinoma cells, indicating that these functions of GABRP are mediated via ERK pathway activation." (PMID 28524180, 2017). "Moreover, we analyzed the DNA methylation status of the GABRP promoter using our previously established ovarian cancer xenograft mouse model to determine whether the differential expression of GABRP in metastatic tissues is epigenetically regulated." (PMID 28524180, 2017). "Hence, we speculate that ovarian carcinoma cells with upregulated GABRP expression, due to the hypomethylation of specific GABRP promoter CpG sites, acquire aggressive phenotypes, which subsequently leads to their metastasis." (PMID 28524180, 2017). "Finally, we analyzed ovarian cancer patient samples to determine whether GABRP expression and/or epigenetic modifications are clinically relevant." (PMID 28524180, 2017).
breast tumors (3 papers, 2019 to 2024). "Among others, SERPINB5, DSC3, and GABRP have also been linked with malignant neoplasms of the breast." (PMID 39580456, 2024). "The pi subunit of the GABA receptor (GABRP) promotes cellular protrusions and migration and is upregulated in basal-like primary breast tumors that result in brain metastases." (PMID 30651600, 2019).
pancreatic ductal adenocarcinoma (3 papers, 2017 to 2022). An infiltrating adenocarcinoma that arises from the epithelial cells of the pancreas. "In pancreatic ductal adenocarcinoma, KCNN4 was reported to interact with GABRP to induce Ca2+ entry, which leads to the activation of NF-κB signaling and ultimately promotes macrophage infiltration." (PMID 35689211, 2022). "Higher expression levels of GABRP have been observed in all grades of pancreatic ductal adenocarcinoma (PDAC) than in healthy control pancreatic tissues, implying that GABRP plays a critical role in the early stages of pancreatic carcinogenesis 29,116,117." (PMID 34790061, 2021).
cervical cancer (2 papers, 2021 to 2025). A primary or metastatic malignant neoplasm involving the cervix. "These high expression levels of GABRP were shown to reverse the effects of miR-320c and increase the migratory potential of cervical cancer cells." (PMID 34790061, 2021). "Western blotting studies have indicated that cervical cancer cells that exhibited higher expression levels of miR-320c had significantly lower protein expression levels of GABRP and lower migratory potential 105, implying a possible role for GABRP in metastatic cervical cancer." (PMID 34790061, 2021).
lung carcinoma (2 papers, 2013 to 2023). "Further evidence for our hypothesis was determined with the indication of the following cancer stem cell markers: GABRP, CTNNB1, and MYC, which are seen in breast, colon, and lung cancer stem cells." (PMID 37370820, 2023).
nicotine addiction (2 papers, 2018 to 2025). "Additionally, KEGG pathway enrichment analysis showed that the co‐expressed genes of GABRP were primarily enriched in pathways related to nicotine addiction, GABAergic synapse, and morphine addiction." (PMID 40459297, 2025).
preeclampsia (2 papers, 2021). Preeclampsia is a hypertensive disorder of pregnancy that is characterized by new-onset hypertension with proteinuria presenting after 20 weeks of gestation, and depending on mild or severe forms may initially present with severe headache, visual disturbances, and hyperreflexia. "Pi, a subunit of gamma-aminobutyric acid type A receptor (GABRP), affects pathways during decidualization of the stromal cell, and also has implications in preeclampsia." (PMID 33923632, 2021).
systemic lupus erythematosus (2 papers, 2015 to 2025). An autoimmune multi-organ disease typically associated with vasculopathy and autoantibody production. "For instance, GABRP polymorphisms correlate with susceptibility to systemic lupus erythematosus, and specific mutations potentially exacerbate immune checkpoint inhibitor-induced hepatotoxicity." (PMID 40901676, 2025).
acinic cell carcinoma (1 paper, 2023). "Several genes that are known to be important in ACC tumors are highlighted with black dots at right, including (from top to bottom) EN1, GABRP, MYB, MYBL1 and NFIB, all of which are expressed more highly in the ACC tumors than in the normal salivary gland or acinic cell carcinoma samples (at left)." (PMID 36900183, 2023).
Arrhythmia (1 paper, 2025). Any cardiac rhythm other than the normal sinus rhythm. "Clinically, understanding the role of GABRP in calcium signaling pathways could provide insights into potential dysregulations in cardiac development relevant to PFO and point to pathways that might influence susceptibility to PFO-related complications like arrhythmias in the future." (PMID 40901676, 2025).
Cognitive impairment (1 paper, 2022). Abnormal cognition is characterized by deficits in thinking, reasoning, or remembering. "This study identified GABRP as one of the core target proteins of the Shunaoxin pill for preventing diabetes-related cognitive impairment." (PMID 36341127, 2022). "According to previous studies, GABRP may protect against diabetes-related cognitive impairment by maintaining normal metabolism and glucose stability." (PMID 36341127, 2022). "Active ingredients of the Shunaoxin pill may alleviate cognitive impairment in diabetic patients by targeting the proteins OPRK1, GABRA5, GABRP, and SCN3B." (PMID 36341127, 2022).
colon adenocarcinoma (1 paper, 2022). "In colon adenocarcinoma, GABRP is associated with a prognostic factor." (PMID 35846884, 2022).
colorectal cancer (1 paper, 2019). A primary or metastatic malignant neoplasm that affects the colon or rectum. "We also observed high expression of GABRP in subsets of gastric and colorectal cancers and lung adenocarcinoma suggesting a broader potential therapeutic appeal." (PMID 31624295, 2019).
congenital heart disease (1 paper, 2025). A heart disease that is present at birth. "Further analysis indicated that GABRP, GJB4, and RTTN were significantly associated with the occurrence of congenital heart disease." (PMID 40901676, 2025).
COVID-19 (1 paper, 2022). A disease caused by infection with severe acute respiratory syndrome coronavirus 2. "Using network pharmacology, we identified 7 core targets of curcumol against COVID-19 and COAD, including GABRD, GABRP, BCHE, CYP3A4, PGR, HSD17B2, and SLC6A3." (PMID 35967794, 2022). "So, the GABAA receptor subtypes GABRD and GABRP might be the promising targets of curcumol for treating COAD and COVID-19." (PMID 35967794, 2022).
epilepsy (1 paper, 2017). A brain disorder characterized by episodes of abnormally increased neuronal discharge resulting in transient episodes of sensory or motor neurological dysfunction, or psychic dysfunction. "Among them, only GABRP has known drug targeting for the treatment of diseases such as insomnia and epilepsy, and this leaves potential for drug repurposing." (PMID 28245581, 2017).
glioblastoma (1 paper, 2025). The most malignant astrocytic tumor (WHO grade IV). "This analysis assessed the immune infiltration of 24 immune cell types in glioblastoma samples with different levels of GABRP expression." (PMID 40459297, 2025). "We conducted ssGSEA analysis using the R‐GSVA package in R‐studio, based on the TCGA dataset, to examine the correlation between GABRP expression levels and immune infiltration in glioblastoma." (PMID 40459297, 2025).
glioma (1 paper, 2025). A benign or malignant brain and spinal cord tumor that arises from glial cells (astrocytes, oligodendrocytes, ependymal cells). "The results showed that higher levels of GABRP expression were linked to lower overall survival rates in patients with various grades of gliomas." (PMID 40459297, 2025). "In gliomas, high expression of GABRP is significantly associated with enhanced tumor cell invasiveness, chemotherapy resistance, and poor prognosis." (PMID 40459297, 2025). "The ROC curve analysis demonstrated the diagnostic value of GABRP in various grades of gliomas." (PMID 40459297, 2025). "We investigated GABRP protein expression levels in different grades of glioma tissues using the Human Protein Atlas (HPA)." (PMID 40459297, 2025). "GO/KEGG enrichment analysis found that the function of the GABRP gene involves GABAergic synapses, and the enhancement of GABAergic synaptic function has been shown to promote glioma proliferation." (PMID 40459297, 2025). "To understand the biological functions of GABRP in lung squamous carcinoma, we used the LinkFinder module of the LinkedOmics website to detect the co‐expression patterns of GABRP in gliomas from the TCGA database." (PMID 40459297, 2025). "The results indicated that GABRP expression levels in gliomas were significantly higher than those in adjacent normal tissues." (PMID 40459297, 2025). "GABRP was overexpressed in gliomas and other cancers (breast, gastric), correlating with poor prognosis (HR = 1.8, p = 0.008) and enriched immunosuppressive cells (Tregs, M2 macrophages)." (PMID 40459297, 2025). "We investigated the role of the GABRP gene in glioma stem cells by conducting experiments with both normal U87 and U251 cells and their GABRP‐knockout counterparts created through lentiviral transfection." (PMID 40459297, 2025). "We used Kaplan–Meier survival curve analysis to assess how GABRP affects the prognosis of patients with various grades of gliomas." (PMID 40459297, 2025). "Functional studies included GABRP knockdown in glioma cells (U87/U251) via lentiviral RNAi, proliferation/migration assays (CCK‐8, scratch test), and pathway analysis." (PMID 40459297, 2025). "Studies have shown that GABAergic signals promote cell migration in gliomas by activating chloride channels, and targeted inhibition of GABRP may reverse this effect and weaken its ability to recruit regulatory T cells (Tregs) and M2 macrophages, thereby relieving immunosuppression." (PMID 40459297, 2025). "Further analysis of GABRP expression levels in different grades of gliomas showed that GBMLGG (low‐grade glioma) included 706 glioma tissues and 50 adjacent normal tissues, while GBM (high‐grade glioma) included 174 glioma tissues and 5 adjacent normal tissues." (PMID 40459297, 2025).
Hepatitis (1 paper, 2025). Inflammation of the liver. "Four interesting SNPs possibly associated with ICI-induced hepatitis were identified in our tumour specimens: three of them, GABRP rs11743438, GABRP rs11743735, and PACRG rs55733913 were found linked to a higher risk of hepatitis, while RGMA rs4778080 seemed to protect against this adverse event." (PMID 41153639, 2025).
heroin addiction (1 paper, 2020). "In the present study, our results showed that GABRP methylation was elevated in the NAc of heroin self-administration rats; however, mRNA expression remained unchanged during heroin addiction." (PMID 33551813, 2020).
invasive breast carcinoma (1 paper, 2012). A carcinoma that infiltrates the breast parenchyma. "These investigators evaluated 203 newly diagnosed invasive breast cancers and showed that higher GABRP gene expression was more common in younger women with a limited history of lactation after pregnancy study." (PMID 22792365, 2012).
nasopharyngeal carcinoma (1 paper, 2022). A carcinoma arising from the nasopharyngeal epithelium. "Hypomethylated high-expression genes, including GABRP identified from GEO datasets and a GEO2R online analysis, suggested it to be a potentially effective biomarker for nasopharyngeal carcinoma (Wu, Zhou & Sun, 2020)." (PMID 35846884, 2022).
neuropathy (1 paper, 2022). A disorder affecting the nervous system that manifests with pain, tingling, numbness, and/or muscle weakness. "Specifically, these DEGs were associated with neuropathy-related pathways, such as GABRD, GABRP, TBX1, and SOX10, and inflammatory responses such as CXCL3, CXCL12, TNF, and IL6." (PMID 36147849, 2022).
pancreatic adenocarcinoma (1 paper, 2022). "Using 178 pancreatic adenocarcinoma patient samples, CD44 and GABRP expressions were significantly co-expressed in the linear regression model." (PMID 35846884, 2022).
schizophrenia (1 paper, 2021). A major psychotic disorder characterized by abnormalities in the perception or expression of reality. "CpG sites conforming the black module were enriched in morphine addiction (GABBR2, GABRP and PDE4B), and polymorphisms of the PDE4B gene have been associated with susceptibility to schizophrenia." (PMID 34579086, 2021).
tumor (20 papers, 2007 to 2026). "As a member of the γ‐aminobutyric acid (GABA) receptor family, the association between GABRP's cancer‐promoting mechanism and tumor microenvironment remodeling provides a new direction for targeted intervention." (PMID 40459297, 2025). "Moreover, the additional loss of the small 5q35.1 segment in the latter tumour was substantiated by the MLPA analysis with the GABRP probe." (PMID 21931686, 2011). "According to our research findings, GABRP is a key oncogene that promotes tumor invasion and cell migration in cancer, and the use of Amentoflavone can effectively treat tumors." (PMID 40459297, 2025). "Tumor cells control the release of GABA via GABRP, which changes the composition of immune cells in the tumor microenvironment." (PMID 40459297, 2025). "Our findings indicate that in various cancers, tumor cells increase GABRP gene expression, which alters the tumor microenvironment and leads to an excess of suppressive immune cells, facilitating immune evasion." (PMID 40459297, 2025). "In summary, our research shows that the primary target of immune‐suppressive tumor microenvironments in pan‐cancer is the GABRP gene." (PMID 40459297, 2025). "By understanding the mechanisms by which GABRP influences the tumor microenvironment and immune evasion, we can pave the way for innovative strategies in cancer diagnosis and therapy, ultimately improving patient outcomes." (PMID 40459297, 2025). "This occurs because cancer cells can continuously produce excessive GABA by upregulating GABRP gene expression, which affects the tumor microenvironment." (PMID 40459297, 2025). "Emerging research indicates that GABRP is not only essential for central nervous system function but also significantly influences tumor initiation and progression, linking its roles in both areas." (PMID 40459297, 2025). "In the tumor microenvironment, the high expression of GABRP specifically inhibits the proliferation and activity of immune cells." (PMID 40459297, 2025). "High expression of GABRP can be accompanied by the generation of more suppressive immune cells, resulting in suppressive tumor microcircles and immune escape of pan‐cancer tumor cells." (PMID 40459297, 2025). "In pan‐cancer, cancer cells upregulate the expression of the GABRP gene, regulate the tumor microenvironment to produce excessive suppressive immune cells, and cause tumor immune escape." (PMID 40459297, 2025). "The elevated levels of GABRP function as a “protective barrier” for pan‐cancer tumor tissues, effectively preventing recognition and clearance by normal immune cells." (PMID 40459297, 2025). "The increased expression of the GABRP gene is crucial for tumor cells to evade immune surveillance, as it leads to a higher release of GABA." (PMID 40459297, 2025). "In our research findings, as shown, high expression of the GABRP gene in cancer cells affects tumor development, progression, and response to immunotherapy." (PMID 40459297, 2025). "Part of them have been documented to be tumor promoter genes of PC, such as GABRP, CEACAM5, CEACAM6 and CST1." (PMID 31706267, 2019). "Nevertheless, these results demonstrate an important role for GABRP in sustaining tumor growth both in vitro and in vivo, which is an advantage for a potential ADC target." (PMID 31624295, 2019). "To examine the effect of GABRP expression on tumor growth, we knocked down GABRP expression in five cell lines, and overexpressed it in GABRP-low MDA-MB-231 cell line." (PMID 31624295, 2019). "Genes encoding proteins involved in ion and electron transport (CYB5R2, GABRP), and genes encoding proteins with transcription factor and regulator activity (ELF5, ID4) were downregulated in both populations of tumor cells." (PMID 17389037, 2007). "Therefore, GABRP overexpression can promote the accumulation of suppressive immune cells, leading to immune evasion by tumor cells across various cancers." (PMID 40459297, 2025).